CCL2 (C-C motif chemokine ligand 2)
Diseases named in the same sentence as CCL2 in open-access papers (continued):
Sharing a sentence is not in itself a finding about the gene and the disease.
breast cancer (continued). "Moreover, TGF-β stimulated CCL2 expression and then induced monocytes/macrophages to secrete Th2-attracting chemokines into a breast cancer MDA-MB-231 cell tumor microenvironment." (PMID 30034291, 2018). "Indeed, CCL2 neutralization in mice inhibited lung metastasis in four syngeneic mouse models of metastatic breast cancer, by retaining monocytes in the bone marrow." (PMID 30597969, 2018). "Differences in transcriptional programs in monocytes deficient in CCR2 vs. CCL2 might explain these disparate effects of CCR2 vs. CCL2 disruption on progression of mammary carcinoma." (PMID 30233579, 2018). "In conclusion, the link between CCL2 in breast cancer metastasis remains obtuse." (PMID 28143493, 2017). "Analysis of the relationship between CCL2 levels and relapse free survival in humans revealed that overall survival is not significantly different between high CCL2 expressing and low CCL2 expressing breast cancer patients grouped together." (PMID 28143493, 2017). "We previously established the 4T1E/M3 highly bone marrow metastatic breast cancer cell line and showed that the chemokine CCL2/MCP-1 negatively regulates the cells' growth, migration, and metastasis, while BMP7 signaling increases the metastatic potential of these cells." (PMID 28197418, 2017). "IL-1β indirectly induces motility in cancer cells through mesenchymal stem cells (MSC)-dependent release of chemokines such as CXCL1, 2, 3, 5, 6, 8, CCL2, 3, 5, and 20 suggesting correlation between interaction of these cells and the metastatic potential of the breast cancer cells." (PMID 28609459, 2017). "In breast cancer the recruitment of inflammatory monocytes to primary and secondary tumor sites has been shown to be mediated by secretion of chemokine (C-C motif) ligand 2 (CCL-2) by tumor and stromal cells." (PMID 28790339, 2017). "Moreover, CCL2 was been reported to increase the cytotoxicity of neutrophils against murine and human breast cancer models, an activity referred to as ‘entrainment’." (PMID 28143493, 2017). "The role of the chemokine CCL2 in breast cancer is controversial." (PMID 28143493, 2017). "Moreover, increased CCL2 produced by stromal cells in the tumor microenvironment has been reported to promote metastasis of 4T1 TN breast cancer cells and ER+ breast cancer to the lung and to support a cancer stem cell phenotype." (PMID 28143493, 2017). "However, with some subtypes of breast cancer, patients expressing high levels of CCL2 exhibited improved RFS." (PMID 28143493, 2017). "CCL2 can be highly expressed by both the tumour and surrounding stromal cells in breast carcinomas." (PMID 28077158, 2017). "CCL2 is overexpressed at tumor sites, malignant pleural effusions, and sera of breast cancer patients, and its increased levels in the tumor microenvironment and circulation were associated with disease progression, early relapse, tumor grade and aggressiveness, and poor prognosis." (PMID 26885690, 2016). "CCL2 has been described to indirectly promote breast cancer metastasis through the induction of pro-metastatic macrophages yet there is evidence for anti-metastatic action of CCL2 that are mediated by the entrainment of neutrophils that reduce metastatic seeding of the lung." (PMID 27626697, 2016). "As an example of the paradoxical effect of CCL2, it has been reported that interruption of CCL2 inhibition accelerates breast cancer metastasis through angiogenesis, and that anti-IL-6 treatment after interruption of anti-CCL2 therapy can prevent lung metastases." (PMID 27136535, 2016). "Several groups have recently reported that blocking CCL2 signaling may be effective in breast cancer and metastatic breast cancer patients." (PMID 27058904, 2016). "Tissue CCL2 content predicts poor clinical outcome in colorectal cancer and breast cancer." (PMID 27058904, 2016).
breast cancer (continued). "Overexpression of CCL2 in the tumor epithelium correlates with tumor grade and poor patient prognosis in various tumor types including: gliomas, prostate cancers, ovarian cancers and breast cancers." (PMID 27283985, 2016). "Interestingly, an analysis of serpinE2 in the TCGA breast carcinoma dataset using the cBioPortal showed a correlation between the RNA levels of CCL2 and serpinE2." (PMID 27793045, 2016). "The MMTV-neu model may specifically highlight this discrepancy since the phenotypes of Ccl2-/- and Ccr2-/- mice are similar in polyoma middle T antigen-driven mammary carcinoma." (PMID 27820834, 2016). "We examined the behavior of these mammary carcinomas in mice carrying targeted deletions of Ccl2 or Ccr2, as well as wild type mice treated with a small molecule antagonist of CCR2, and explored the effects of this chemokine ligand/receptor pair on the tumor microenvironment." (PMID 27820834, 2016). "Also, that in addition to CCL2, leptin and lauric acid, there are additional unidentified paracrine factors promoting monocyte chemotaxis to the obese mammary tumor microenvironment." (PMID 25599228, 2015). "CCL2 is another possible target fitting this strategy since CCL2 neutralizing antibody can suppress Ccl3 expression in MAMs as well as their recruitment following mammary tumor metastasis." (PMID 26275794, 2015). "This approach could be combined with treatments with CCL2 blocking antibody and the anti-leptin signaling peptide in obese tumor-bearing mice, aiming to inhibit macrophage recruitment/activity in the mammary tumor microenvironment." (PMID 25599228, 2015). "Knockdown of CoREST1 in MDA-MB-231 breast cancer cells resulted in downregulation of several pro-inflammatory factors at both the RNA and protein level, including CCL2, one of the key chemokines that promotes infiltration of macrophages and monocytes into the tumor microenvironment." (PMID 25793264, 2015). "Indeed CCL2 depletion by antibody treatment and genetic modification results in reduced metastasis and improved survival in multiple experimental models of mammary cancer." (PMID 25990313, 2015). "Here, we identified the impact of TNF-α and IL-1β on the inflammatory phenotype of CAFs and MSCs by determining the expression of inflammatory chemokines that are well-characterized as pro-tumorigenic in breast cancer: CCL2 (MCP-1), CXCL8 (IL-8) and CCL5 (RANTES)." (PMID 25928089, 2015). "BMDMs exposed to 4T1 mammary carcinoma-conditioned medium demonstrated enhanced production of pro-inflammatory cytokines tumor necrosis factor α, interleukin-6, and CCL2 in response to lipopolysaccharide (LPS) while production of interleukin-10 remained unchanged." (PMID 26177198, 2015). "Furthermore, CCL2/CCR2 (CCL2 receptor) chemokine signaling seems to be implicated in cell migration and its overexpression is associated with breast cancer metastasis to both lung and bone." (PMID 24591761, 2014). "CCL2 recruits macrophages to facilitate metastasis of breast cancer." (PMID 25193015, 2014). "Furthermore, functional single-nucleotide polymorphisms (SNPs) located in the promoter region of CCL2 and CXCL8, and thus regulating transcription of these chemokines, have been associated with clinical breast cancer outcome." (PMID 24260134, 2013). "Others, like us, did not observe associations between CCL2-rs1024611 and breast cancer risk among Caucasians." (PMID 23991131, 2013). "Also, a recent study identified a novel role for CCL2 showing that CCL2 stimulates the self-renewal of stem/progenitor cells in breast cancer." (PMID 23982944, 2013). "CCL2 is one of the chemokines essential for breast cancer development and progression." (PMID 23874655, 2013). "Similarly, consistent with our results, CCL2 has also recently been reported to instigate breast cancer metastasis to the lung and bone." (PMID 21283672, 2011).
breast cancer (continued). "Furthermore, in breast cancer–associated fibroblasts (CAFs), SNHG5 stabilizes ZNF281 mRNA through an m6A-dependent mechanism, upregulating CCL2/CCL5 expression and activating p38 MAPK signaling, which enhances vascular permeability and neovascularization to facilitate PMN formation." (PMID 41550840, 2026). "CCL2 is a key chemokine involved in cancer development, with signaling pathway significantly contributing to the progression of various cancers The CCL2 drives tumor growth through the PI3K/AKT/mTOR pathway, which is associated with poor prognosis in breast cancer." (PMID 40761779, 2025). "Furthermore, in breast cancer, CCL2 and CCL5 expression is restricted not only to tumor cells but also to cells of the tumor microenvironment, including fibroblasts, endothelial cells, mesenchymal stem cells, smooth muscle cells and immune cells such as tumor-associated macrophages and T cells." (PMID 38928033, 2024). "Finally, CCL2 blocking significantly improved the survival of breast cancer-bearing mice." (PMID 38786066, 2024). "In addition to its role of immunosuppression via regulating PD-1 expression in macrophages surrounding breast cancer cells, CCL2 may also influence breast cancer cell proliferation and cell-cycle progression through SRC and PKC activation." (PMID 39703847, 2024). "Genetic polymorphisms of CCL2 and CXCL12 may influence the binding of transcription factors to these genes, affecting promoter activity and gene transcription, and therefore they may have varying impacts on developing breast cancer." (PMID 39703847, 2024). "CCL2 and CCR4 or CCR2 have been proposed as a potential target for decreasing myeloid-derived suppressor cells (MDSCs) and tumor-associated macrophages (TAMs) recruitment in prostate cancer, breast cancer, malignant glioma, colorectal cancer, and lung carcinoma." (PMID 39046599, 2024). "However, the association between SNPs in the CCL2 and CXCL12 genes and the susceptibility to breast cancer remains unclear." (PMID 39703847, 2024). "Moreover, LC3-loaded EVs released by breast cancer cells could induce lung fibroblasts to produce CCL2 by the HSP60-TLR2-MyD88-NF-κB pathway." (PMID 37534210, 2023). "Therefore, inhibition of CCL2 or CCL2/CCR2 may be a potential approach to the treatment of breast cancer." (PMID 36403055, 2022). "Furthermore, CCL2 plays an important function in the drug-resistant of breast cancer cells." (PMID 36403055, 2022). "Here, we show that CCL2 enhanced expression of glycolytic enzymes corresponding to increased enzymatic activity, which could help to confer a growth and invasive advantage to breast cancer cells." (PMID 35405500, 2022). "Furthermore, CAFs may also regulate monocyte and macrophage recruitment and differentiation via secretion of CCL2, contributing to immune suppression and metastasis in breast cancer cells." (PMID 34948097, 2021). "Moreover, CCL2 regulated breast cancer cell growth and migratory ability, whereas RS 102895 could attenuate these regulatory effects partially due to the downregulation of MMP‐9 expression." (PMID 34464477, 2021). "Additionally, a high expression level of CCL2 in the stroma is associated with infiltration of CD163+ macrophages and poor progression‐free survival (PFS) of patients with estrogen receptor‐positive breast cancer." (PMID 35250965, 2021). "Based on these data, we hypothesize that ASS1 expression restores arginine metabolism in M231-ADIR cells, whereas TREM1 expression stimulates AKT/mTOR/STAT3 and a CCL2 feed-forward loop to provide survival signals contributing to ADI resistance in breast cancer cells." (PMID 33664852, 2021). "Finally, elevated CCL2 recruit macrophages to promote breast cancer metastasis." (PMID 33868269, 2021). "Importantly, CCL2, along with other inflammatory cytokines, is a modulator of cancer invasiveness by affecting tumor microenvironment, and its higher expression predicts worse outcomes for breast cancer patients." (PMID 32455851, 2020).
breast cancer (continued). "To further confirm whether CCL2 and CXCL5 function as pivotal chemokines mediating S100A14-induced breast cancer metastasis in vivo, we used the 4T1 orthotopic transplantation model in which mice were treated with CCL2- and CXCL5-neutralizing antibodies or IgG control antibodies." (PMID 32483412, 2020). "Thus, it might be an effective combinatorial treatment with PARP1 and CCR2 inhibitors to achieve better outcomes where CCL2 levels are determined to be high, particularly in breast cancer, as well as other solid tumors." (PMID 32455851, 2020). "Understanding how CCL2 expression recruits myeloid-lineage cells to promote tumor progression and desmoplasia may lead to identification of new therapeutics to enhance treatment options for obese breast cancer patients." (PMID 32731354, 2020). "Therefore, the use of CCL2 siRNA, CCR2 siRNA, CCL2-neutralizing antibodies, CCL2 inhibitors or CCR2 antagonists has given promising results in the therapy of cancers such as breast cancer, glioma, and hepatocellular cancer in laboratory animals inoculated with cancer cells." (PMID 33182504, 2020). "Importantly, S100A14 expression is highly associated with CCL2 and CXCL5 expression in breast cancer tissue and serum samples, supporting our hypothesis that S100A14 regulates CCL2/CXCL5 expression in a physiological context." (PMID 32483412, 2020). "However, the contributions of ALDH1A1 and HTRA2 to breast cancer cell growth and invasion may depend on a complex set of factors involving differences in CCL2/CCR2 signaling among breast cancer cell lines." (PMID 31208996, 2019). "In addition, in breast cancer lung metastasis mouse models, CCL-2 secreted by both tumor cells and endothelial cells preferentially recruited C-C chemokine receptor type 2 (CCR2+) macrophages to lungs, resulting in increased metastatic seeding and tumor outgrowth." (PMID 31130637, 2019). "Our data corroborate with previous literature studies showing the significant role of CCL2 signaling in breast cancer cells and indicates that targeting CCL2 signaling pathway may affect various mechanisms involved in cancer progression, hence representing an attractive therapeutic target." (PMID 31665136, 2019). "Indeed, in the MMTV-PyMT mouse model of spontaneous breast cancer, CCL2, released by either tumor cells or stromal cells at the metastatic lung niche, induces the recruitment of CCR2-expressing iMo, which in turn favor the extravasation of tumor cells, through the release of VEGFA." (PMID 31447834, 2019). "CCL2 may promote breast cancer cell development by many mechanisms." (PMID 30151375, 2018). "Furthermore, CCL2 may directly promote tumor cell migration and, remarkably, may favor the extravasation and seeding of breast cancer cells through the recruitment of inflammatory monocytes to the pre-metastatic foci." (PMID 30591657, 2018). "However, the relevance of Twist expression with CCL2 modulation in human breast cancer still remains unclear." (PMID 29934505, 2018). "And another plausible explanation might be the possibility that more aggressive ER negative breast tumors are associated with higher CCL2 expression since our work also revealed that tumors with high levels of CCL2 staining showed higher aggressiveness of breast cancer." (PMID 29934505, 2018). "Here we examined the levels of CCL2 in 4 breast cancer cell lines along with 57 human breast cancer specimens and found them significantly increased with presence of 17β-estradiol (E2) in estrogen receptor (ER)-positive breast cancer cells, while anti-estrogen treatment weakened this enhancement." (PMID 29934505, 2018). "Importantly, CCL2 signalling increases the cytotoxicity of neutrophils against murine and human breast cancer models, thus suggesting that it might trigger neutrophil anti-metastatic capacity." (PMID 30591657, 2018).
breast cancer (continued). "These biological characteristics are strikingly similar to the mammary glands of Mmtv-Ccl2 transgenic mice, in which overexpression of CCL2 caused increased abundance of stroma, collagen thickness, mRNA encoding TIMP3 and elevated risk of DMBA-induced mammary cancer." (PMID 28077158, 2017). "While other studies have demonstrated CCL2 as a prognostic factor by evaluating selected cell populations or distinct location of metastases, we have chosen to look at a large dataset of more than 3000 primary breast cancers to evaluate the overall expression of CCL2 mRNA." (PMID 28143493, 2017). "Elevated levels of CCL2 in breast cancer biopsies correlate with increased TAM accumulation, more extensive tumor vascularization, and more aggressive clinical behavior and at least a portion of CCL2’s effects may be attributed to its ability to stimulate angiogenesis." (PMID 27820834, 2016). "Notably, CCL2 expression was found to be dependent on MyD88 in murine mammary carcinomas cells." (PMID 27312666, 2016). "Interestingly, as opposed to other tumor models where adipocytes are the main producers of CCL2, in our E0771 tumor model, even adipocytes from obese adipose tissues produced negligible amounts of CCL2, and it is the E0771 mammary tumor cell line that is the main producer of this chemokine." (PMID 25599228, 2015). "We have previously shown that T lymphocytes from mammary tumor-bearing mice produce CCL2 and that T cell-derived CCL2 could also contribute to tumor growth directly via its pro-angiogenic activity and indirectly by attracting monocytes that secrete growth-promoting factors." (PMID 24399973, 2013). "Among the upregulated genes in the peritumoral adipose tissues of obese breast cancer patients, C‐C chemokine receptor 2 (CCR2), a receptor for CCL2, was identified." (PMID 41160815, 2026). "In breast cancer, pancreatic cancer, and other solid tumors, high tumor CCL2 expression is associated with improved responsiveness to CCR2 or CSF1R inhibitors, indicating that CCL2 expression levels may serve as a predictive biomarker concerning the efficacy of TAM‐targeted therapy." (PMID 41426206, 2026). "Here, we showed that CCL2/HGF co-treatment increased cell growth, survival, and invasion in DCIS.com and HCC1937 breast cancer cells over CCL2 or HGF treatment alone." (PMID 40736024, 2025). "Because we previously reported that CXCL5, CCL2, CCL3, and CCL5 occur at low levels in CM collected from aggressive breast cancer cell lines, here we focused on other abundantly secreted chemokines." (PMID 40833805, 2025). "CCL2 also induces ERK/GSK-3β/Snail signaling to promote EMT and the migration of MCF-7 human breast cancer cells." (PMID 41341593, 2025). "Six of the genes (CASP1, CCL2, ADGRE5, IL3RA, RSPO1, and STAB1) are co‐expressed with the CH25H gene in both cancers, while two genes (ANPEP in breast cancer and CCL8 in prostate cancer) are exclusively co‐expressed with the CH25H gene in one of the tumors." (PMID 41159143, 2025). "Our results showed that the CCL2 concentration in the KPC cell supernatant was significantly higher compared to that of J774A.1 macrophages, 4T1 breast cancer cells, and CT26 colon cancer cells." (PMID 40700478, 2025). "It would be of interest to conduct further studies on how CCL2 and HGF regulate breast cancer cell activity through genetic and epigenetic mechanisms." (PMID 40736024, 2025). "Overall, these studies provide insight into how CCL2 and HGF function to coordinate breast cancer growth, survival, invasion, and metabolism, and demonstrate that targeting CCR2 and MET inhibit DCIS progression." (PMID 40736024, 2025). "Given the alterations in AKT, AMPK, p42/44MAPK and PKC signaling with CCL2 and HGF treatment, we determined the contributions of these pathways to CCL2 and HGF-mediated metabolism in breast cancer cells." (PMID 40736024, 2025).